APOE (apolipoprotein E)
Diseases named in the same sentence as APOE in open-access papers (continued):
Sharing a sentence is not in itself a finding about the gene and the disease.
Obesity (continued). "However, the interaction between obesity and APOE to regulate the pathogenesis of AD remains unclear." (PMID 37686334, 2023). "In addition, the frequency of medical co-morbidities including differences in insulin resistance, obesity, lipid profile-modifying medications, racial differences, and relative numbers of APOE ε4 carriers may impact differences in results between cohorts." (PMID 36927447, 2023). "Therefore, combined with the functional and pathway annotations obtained from the bioinformatics analysis in this study, it is suggested that obesity may induce the occurrence of AD through the regulation of lipid metabolism by APOE." (PMID 37686334, 2023). "APOE ε3 carriers, as the largest group in AD population, might be more susceptible to obesity, while the risk of AD in APOE ε2 and APOE ε4 carriers might not be induced by obesity." (PMID 37686334, 2023). "Although the APOE 4 gene significantly increases the likelihood of developing AD, many individuals who are APOE4 carriers do not develop the disease; it is hypothesized that APOE4 interacts with several factors, including obesity, that increase AD risk." (PMID 35128745, 2022). "Apolipoprotein E could be the link between APOE genetic polymorphism and obesity." (PMID 35205269, 2022). "It is increasingly recognized that APOE ε4 may interact with obesity to augment disruptions in lipid, glucose, insulin, and immune response metabolism and that such adverse interactions may increase the vulnerability of medial temporal lobe structure to neurodegeneration." (PMID 35303671, 2022). "Despite this, to our knowledge, no published study has examined brain activity of APOE ε4 allele carriers with overweight/obesity during a working memory task, let alone while controlling for potentially confounding factors such as body weight and cerebral perfusion." (PMID 36504632, 2022). "Therefore, we hypothesized that obesity in patients with schizophrenia may also be influenced by APOE E4 and SIRT1 genes, but these conclusions need to be verified in future studies." (PMID 34285334, 2021). "However, we did not specifically investigate insulin resistance and glucose metabolism in the present study, and our sample size may not have been sufficiently large to detect any interactive effects between APOE genotype and obesity-related mechanisms in men." (PMID 30735826, 2019). "However, the interactions between obesity and APOE genotypes are less clear." (PMID 30586872, 2018). "Additional studies should determine if truncated or mutated APOE forms could also serve as biological anti-obesity drugs for WAT mitochondrial metabolic activation towards non-shivering thermogenesis." (PMID 29770778, 2017). "It has been suggested that the APOE-obesity interaction may intensify insulin resistance in men." (PMID 28740125, 2017). "Moreover, mice on ApoE−/− background suffer from resistance to diet-induced obesity, which additionally may hinder a potential difference in body weight of DKO mice compared to control animals." (PMID 28380440, 2017). "Therefore, we speculated that the reduction of hepatic NAMPT expression in both HFD-fed C57BL/6J and ApoE KO mice might be a compensatory down-regulation to counteract the metabolic stress imposed by obesity or abnormal cholesterol metabolism." (PMID 27229177, 2016). "We could show for the first time in children that rs599839 (SORT1) and rs4420638 (APOE) are strongly associated with alterations in blood lipid levels independent of the presence and degree of obesity." (PMID 26375028, 2015). "In addition, APOE correlates with inflammation in adipose tissue in high-fat diet-induced obesity." (PMID 24621099, 2014). "Interestingly, ApoE has been reported to be crucial for the accumulation of triglycerides in mouse adipocytes and also appears to have an important function in adipocyte differentiation and obesity." (PMID 19823686, 2009).
Obesity (continued). "In the early stages of obesity, ligand–receptor interactions involving LPL, LRP1, and ApoE in ATM contribute to lipid signaling, which regulates inflammation and shapes the metabolic microenvironment of adipose tissue." (PMID 40244284, 2025). "Interestingly, in genetically obese mice additional APOE deficiency prevents severe adiposity and ectopic lipid deposition in the liver emphasizing the complexity of the interaction of APOE with obesity, ectopic and nonectopic lipid deposition and related pathologies." (PMID 37450924, 2024). "Other factors that contribute to diet-induced obesity include APOA1, the most abundant protein of HDL, APOE, an important protein of HDL/LDL/VLDL, and the functional ligand of an LDL receptor." (PMID 37375802, 2023). "In summary, our data demonstrated that ApoE ablation alleviates obesity and dysregulation of glucose metabolism at the expense of inciting chronic inflammation through NLRP3 inflammasome in obesity." (PMID 38062308, 2023). "Recent studies from our laboratory have documented that global TSP-1 deletion in vivo reduces atherosclerotic lesion burden in ApoE–/– mice in response to both STZ-induced hyperglycemia and exogenous leptin administration, mimicking obesity." (PMID 36505365, 2022). "In MAFLD patients with overweight/obesity, there were dose–response relationships between moderate-to-severe steatosis and total cholesterol, triglyceride, HDL-c, LDL-c, ApoB, ApoE, and Lp(a) (all p for trend <0.05)." (PMID 34899591, 2021). "In overweight or obesity MAFLD patients, total cholesterol, LDL-c, ApoB, ApoE, and Lp(a) achieved AUCs of 0.679, 0.677, 0.689, 0.684, and 0.674, respectively (all p < 0.02)." (PMID 34899591, 2021). "In those with overweight/obesity, there were dose–response relationships between moderate-to-severe steatosis and total cholesterol, triglyceride, HDL-c, LDL-c, ApoB, ApoE, and Lp(a)." (PMID 34899591, 2021). "At the same time, we found that ApoE-knockout mice fed with a high-cholesterol and high-fat diet (HCD) developed obesity, which was improved in the PYC-treated groups." (PMID 29577045, 2018). "The in vivo studies using both wild type (WT) and apolipoprotein E (ApoE) knockout mice fed with high fat diet (HFD) showed the beneficial effects of small-molecule EGFR inhibitors, AG1478 and 542, against obesity-induced myocardial injury." (PMID 27087279, 2016). "The aim of this study was to assess the effect of APOE genotypes, the intake of saturated fatty acids (SFA), and obesity on serum lipid levels in Lithuanian adult population." (PMID 22844488, 2012). "Oxidised ApoE and ApoC‐III peptide fragments were also significantly correlated with obesity, insulin resistance, dyslipidaemia and transaminases, suggesting a potential link between circulating apolipoprotein oxidation and systemic/hepatic metabolic dysfunction." (PMID 39822152, 2025). "Furthermore, during certain infections and chronic inflammation such as obesity, HDL composition and size also change, reducing particularly the content of certain apolipoproteins, such as APOA1 and APOE." (PMID 36969259, 2023). "These include age and APOE genotype as well as untreated MDD and obesity." (PMID 37304012, 2023). "In this study, we demonstrate for the first time that long-term EGCG intervention reduces PFDA-exacerbated obesity and hepatic lipid accumulation in HFD-fed mice, which is consistent with the findings in apolipoprotein E knockout mice and HFD- and streptozotocin-induced type 2 diabetic mice." (PMID 38067561, 2023). "Sensitivity analyses conducted on the subset of females (n = 60) revealed similar trends of neuroprotection by obesity and negative synergistic effects of BMI APOE-ε4 on left CA1 volume." (PMID 37731955, 2023).
Obesity (continued). "This ancillary study included 48 (n = 24 APOE ε4 carriers; n = 24 APOE ε4 non-carriers), sedentary middle-aged adults (Mean age = 44.63 ± 8.36 years) with overweight/obesity (Mean BMI = 32.43 ± 4.12 kg/m2) who were matched on demographic characteristics." (PMID 36504632, 2022). "Nevertheless, one difference between ApoE−/− mice and APOE2 mice in response to diet-induced obesity may be due to endogenous expression of apoE in adipocytes." (PMID 36077289, 2022). "The mechanistic role of APOE expression in hypothalamic microglia has not been explored in models of diet-induced obesity, but data from studies in neurodegenerative disease lend clues towards the potential function." (PMID 34122343, 2021). "Surprisingly, we found that S. mansoni infection does not reliably protect female ApoE-/- mice from high fat diet induced obesity or glucose intolerance." (PMID 33417618, 2021). "Surprisingly, systemic protection from the metabolic disease parameters of obesity and glucose intolerance is sex-dependent, as S. mansoni infection fails to protect female ApoE-/- mice from disease." (PMID 33417618, 2021). "Although, the ApoE KO mouse model is not recognized as a susceptible model for obesity and insulin resistance, DKO mice exhibited exaggerated hyperglycemia, as higher fasting glucose levels were observed in DKO mice in comparison to ApoE KO control mice." (PMID 32796650, 2020). "Though the human literature suggests a gene-environment interaction between APOE and obesity in regulating development of AD, this question has not been addressed in experimental models." (PMID 28612048, 2017). "The fact that AdipoR2-/-ApoE-/- mice and AdipoR2+/+ApoE-/- controls were comparable in terms of body weight gain or obesity in this study is however not surprising since ApoE-deficiency has been shown to attenuate diet-induced obesity in mice." (PMID 24324556, 2013). "Because of the increase in GDF‐15 levels in atherosclerotic vessels of apoE−/− mice after CED, we investigated whether GDF‐15 affects obesity and blood lipid concentration using GDF‐15−/−/apoE−/− male mice generated from heterozygous matings." (PMID 23316317, 2012). "This study revealed that, regardless of APOE allele type, both CHC and SC patients consumed a hepatopathogenic-type diet, in line with earlier findings from studies conducted in non-HCV patients with obesity-related dysfunctional metabolism." (PMID 34684338, 2021). "IL-4c injection did not improve obesity or glucose tolerance in HFD ApoE-/- males." (PMID 33417618, 2021). "Apolipoprotein E (APOE) gene polymorphisms might be involved in the pathogenesis of schizophrenia, however, the effect of APOE gene polymorphism on obesity has never been investigated in Chinese aging with schizophrenia." (PMID 34285334, 2021). "After 16 weeks of high fat diet (HF) feeding, both ApoE-/- and ApoE-/-TSP1-/- mice showed almost comparable body weight and fat mass, supporting the previous finding that TSP1 deficiency does not affect the development of obesity." (PMID 25803585, 2015). "In addition to the apparent and expected impact of BMI SDS, rs599839 (SORT1) and rs4420638 (APOE) have a high certainty of affecting LDL-C independent of the degree of obesity." (PMID 26375028, 2015). "As such, we next determine whether ApoE ablation might promote negative glucose balance in obesity." (PMID 38062308, 2023). "However, the mechanism by which apolipoprotein E would influence obesity is not clear." (PMID 21059196, 2010). "Notably, valve dysfunction in the Western diet-induced obesity model was only observed in mesenteric and not in popliteal collecting lymphatics, in contrast to the hyperpermeability of mesenteric collectors and both valve and contractile dysfunction in popliteal collectors of ApoE−/− mice fed a HFD." (PMID 36685213, 2022). "Analysis of gene-diet and gene-obesity interactions did not confirm that the effects of diet and obesity on TC and LDL-C level significantly depended on APOE genotype." (PMID 22844488, 2012).
Obesity (continued). "In addition, obesity significantly increased plasma TNF-α, PAI-1 and resistin levels in ApoE-/- mice but not in ApoE-/-TSP1-/- mice." (PMID 25803585, 2015).
amyloid (373 papers, 2010 to 2026). "APOE ε4 carriership was associated with increased longitudinal cortical amyloid deposition only in individuals with normal baseline CSF amyloid." (PMID 42216672, 2026). "APOE ε4 allele increases the deposition of amyloid protein in the wall of small cortical and meningeal vessels, making it vulnerable to rupture, whereas APOE ε2 mainly causes blood vessels with amyloid deposition to rupture and bleed." (PMID 40051977, 2025). "Although, it was a single case study, the robust protection conferred by the apoE Christchurch variant was reproduced in different laboratories using mouse models of tauopathy and amyloid pathology." (PMID 40275327, 2025). "The number of low scores was significantly related to more amyloid deposition, smaller hippocampal volume, and having one or more copies of the ε4 allele of APOE." (PMID 40842048, 2025). "Structural, functional, and molecular brain imaging, along with CSF biomarkers of amyloid pathology, neurodegeneration, and the presence of a vulnerability-associated APOE genotype, support the diagnosis of AD." (PMID 40164861, 2025). "APOE ε4 is linked to impaired Aβ clearance in the brain, contributing to amyloid plaque buildup, a hallmark of AD." (PMID 39996737, 2025). "Studies in mice and previous data from our lab in xenotransplantation models have shown that both the deficiency of TREM2 and APOE can alter the transcriptional response of microglia to amyloid pathology." (PMID 38654375, 2024). "While APOE plays an important role in lipid transport, specific variants of this gene are strongly associated with AD risk as APOE interacts with amyloid beta in amyloid plaques, a hallmark of the disease." (PMID 39485282, 2024). "The presence of the APOE-ε4 allele increases amyloidosis and is the strongest genetic risk factor for late onset AD." (PMID 39350363, 2024). "In AD mouse models, the primary effect of APOE deficiency is the prevention of amyloid plaque formation." (PMID 39528861, 2024). "In humans, APOE ε4 was strongly associated with increased levels of amyloid deposition in the brain; however, APOE ε4 was also associated with higher tau accumulation independently from its effect on amyloid deposition in AD." (PMID 38049659, 2024). "This study examined the effects of astrocyte-derived human APOE isoforms in APOE-deficient mouse brains on amyloid pathology and related cellular responses." (PMID 39528861, 2024). "Our experiments indicate a central role of the astrocytes in APOE mediated amyloid plaque pathology and in the induction of associated microglia responses." (PMID 39528861, 2024). "Since ApoE status is tightly associated with amyloid and tau pathology, it is possible that the gradient changes we observed in ε4 carriers and participants with higher tau/p-tau levels and lower Aß/p-tau ratio are interlinked." (PMID 37076873, 2023). "ApoE is associated with the formation of amyloid plaques, and ApoE immunotherapy is effective in ameliorating amyloid pathology because it targets ApoE in the plaque core and cerebral blood." (PMID 37705104, 2023). "Both ApoE and amyloid proteins play important roles in amyloidoses as they form two main risk factors for these diseases Amyloid and ApoE proteins possess intrinsically disordered regions." (PMID 36817952, 2023). "The V236E APOE3 mutation has been shown to reduce APOE aggregation, enhance APOE lipidation in human brains, and reduce amyloid pathology and neuritic dystrophy in an AD-like mouse model." (PMID 37131074, 2023). "We also examined the ApoE level-associated novel SNPs in the APOE and non-APOE regions with AD risk and amyloid deposition in the brain." (PMID 37666928, 2023). "Although we focused on APOE-independent sources of AD risk, it is important to note that the number of APOE-ε4 alleles had a comparable or even stronger (in the case of amyloid) effect on the outcomes as the polygenic component indexed with a PRS." (PMID 36909609, 2023).
amyloid (continued). "The association between the presence of ApoE and amyloid in amyloidoses suggests a more general role for ApoE in the fibrillogenesis process." (PMID 36436561, 2022). "LRP1 is also responsible for the endocytosis and degradation of Aβ, or Aβ-ApoE complex, whereby amyloid pathology is enhanced by the APOE4 allele, dependent upon LRP1 uptake." (PMID 34503576, 2021). "Apolipoprotein E (APOE) status is considered one of the most important risk factors for the development of amyloid pathology." (PMID 33786000, 2021). "To further address relevance in human brains, we assessed the association of apoE and αSyn pathology in postmortem brain samples from Lewy body disease patients with minimal amyloid pathology (online resource)." (PMID 34453582, 2021). "Cerebral amyloid pathology, tau pathology, or both are often associated with concomitant neuroinflammation, in which APOE is a crucial player." (PMID 32899606, 2020). "Similar plaque morphology with less fibrillar Aβ, as observed in APP-KI mice, has also been reported in AD mice deficient for TREM2 or APOE that also have less microglial cells recruited to amyloid plaques and display prominent neuritic dystrophies." (PMID 32510331, 2020). "Other cellular and pathological similarities between the Tg‐FDD model and Aβ‐CAA include amyloid‐associated gliosis, a strong inflammatory response, association of ApoE with vascular amyloid deposits, and the presence of perivascular tau aggregates." (PMID 32914559, 2020). "In fact, APOE ε4-mediated Aβ pathology likely depends on LRP1, as LRP1 deficiency in neurons blocks the APOE ε4-mediated exacerbation of amyloid plaque burden in APP/PS1 (PSEN1) double-transgenic mice." (PMID 32859588, 2020). "Conversely, the ApoE2 isoform is protective in AD, suggesting that the mechanistic basis of ApoE-amyloid association differs between AD and CAA." (PMID 32711525, 2020). "Of note, the effects of APOE alleles on tauopathies can be modified by the presence of amyloid pathology, indicating an intricate relationship between the two pathological hallmarks of AD." (PMID 32899606, 2020). "Similar to CSF amyloid, cortical amyloid was significantly associated with APOE-ε4 burden over APOE-ε4 status (28 of 34 regions with PFDR from 0.035 to 6.65e-04)." (PMID 32226939, 2020). "Among older adults with NC from ADNI, volume of WMH and APOE ε4 status were more strongly associated with cortical amyloid status on PET compared to other traditional biomarkers of AD, including FDG-PET and hippocampal volume." (PMID 31351489, 2019). "Plasma concentrations of ApoE, which is the most abundant amyloid-associated protein, were gradually decreased and associated with an increasing degree of amyloid deposition." (PMID 31281565, 2019). "Overall, our results support a model in which amyloid is significantly associated with tau deposition, but with APOE ɛ4 potentially being associated with accelerated tau pathology in key AD regions in the presence of substantial amyloidosis." (PMID 31642932, 2019). "Wild-type or mutated apolipoproteins, evolutionarily related to apoE, have been found in depositions of amyloid fibrils in vivo in several amyloidosis." (PMID 31071995, 2019). "Bexarotene increases ApoE expression rapidly in murine models of AD, and this has been associated with reduction of the amyloid plaque burden and improvement of cognitive function." (PMID 31596896, 2019). "ApoE is a chaperone protein that is widely found to be associated with various amyloid depositions and is considered a risk factor for the onset of amyloidosis." (PMID 31281565, 2019). "Age and APOE ε4 contributed to the model, as in previous studies seeking biomarkers indicative of brain amyloid; unsurprisingly given that both age and APOE genotype are highly associated with amyloid pathology." (PMID 31495601, 2019).